Y_RNA (Y RNA )
Gene: Miscellaneous RNA gene on chromosome 19 (36,203,347 to 36,203,459, reverse strand). Ensembl gene ENSG00000200179.
Homologues: Orthologues: chimpanzee Y_RNA (99% identical), macaque Y_RNA (95% identical). Paralogues in human: RNY1 (86% identical), Y_RNA (82% identical), Y_RNA (81% identical), Y_RNA (80% identical), RNY1P8 (79% identical), Y_RNA (79% identical), Y_RNA (78% identical), RNY1P11 (77% identical), Y_RNA (77% identical), Y_RNA (76% identical), RNY1P7 (75% identical), Y_RNA (75% identical), and 94 more.